MYD88 (MYD88 innate immune signal transduction adaptor)
Diseases named in the same sentence as MYD88 in open-access papers (continued):
Sharing a sentence is not in itself a finding about the gene and the disease.
infection (continued). "Future studies employing infection with mildly virulent E. muris that cause mild/non-lethal ehrlichiosis in mice would provide more insight into the anti-bacterial protective function of MyD88." (PMID 38022511, 2023). "The up-regulatory effect on MyD88 and TRIF may be the result of direct viral interaction or the up-regulation effect on cell-membrane- (TLR2 and TLR4) and endosomal-associated (TLR3, TLR8, and TLR9) TLRs induced by single-PDCoV infection." (PMID 36376395, 2022). "Furthermore, the 10% that did not meet the stringent significance cutoff after infection WT BMDMs could still be identified by MS in this infection, arguing against any unique proteins expressed in MyD88−/− BMDMs." (PMID 36321832, 2022). "In addition, the total number of leukocytes has been shown to be similar in Myd88-deficient and wild-type larvae at 3 and 5 dpf, so it seems most likely that the lower number of immune cell at the site of infection results from a reduced recruitment of leukocytes in the myd88 mutant larvae." (PMID 33559740, 2021). "Moreover, MyD88 was involved in the infection-related morbidity." (PMID 34796128, 2021). "Moreover, since the TLR/MyD88/NF-кB pathway can be activated following infection by many pathogens, it is plausible that regulation of m6A methylation through activation of TLR/MyD88/NF-кB signaling may be a general cellular response to microbial infection." (PMID 34295340, 2021). "Fungal recognition receptors commonly studied on MCs are TLR2/4 and Dectin-1.Upon activated by TLR/MyD88 or Syk pathway, MCs can produce specific cytokines and chemokines which can elicit a direct temporary immune response and recruit some neutrophils to the infection sites." (PMID 34149729, 2021). "Larvae from a myd88 mutant line (myd88-/-) or myd88 knockdown larvae showed decreased induction of pro-inflammatory cytokines, lower production of reactive nitrogen species by neutrophils and attenuated initiation of autophagic defence, resulting in increased rates of infection." (PMID 33559740, 2021). "Furthermore, while MyD88- and IRAK-4-deficient children are at risk of life-threatening invasive bacterial infections early in life, with a mortality rate of approximately 38%, the susceptibility to infection decreases significantly with age." (PMID 34199501, 2021). "However, alternative explanations are possible, such as alterations in haematopoiesis that may be Myd88-dependent, or death of immune cells cell taking place outside the site of infection or at earlier stages." (PMID 33559740, 2021). "However, our original study revealed that mice deficient in MyD88, the adaptor molecule responsible for TLR, IL-1R, IL-18R, and IL-33R signaling, was essential for bacterial containment during acute S. aureus craniotomy infection." (PMID 32290861, 2020). "Besides TLR3, other TLRs target the MyD88 pathway to resist pathogen infection." (PMID 31947624, 2020). "However, the response of MyD88-deficient monocytes to signature pathogens is variable, and the monocyte response per se does not correlate well with the individual risk for infection at the time of testing." (PMID 33424861, 2020). "Regardless of MAL, polymorphism in MyD88 alone did not influence the infection." (PMID 33072109, 2020). "Thus, the intrinsic role of MyD88 in mucosal Tregs during an infection remains to be defined." (PMID 33240286, 2020). "To determine if GRA24 was responsible for protective immunity elicited by cps1-1, we determined how cps1-1 vaccination with or without GRA24 impacted systemic parasite burden in MyD88 deficient mice following challenge infection with virulent RH strain tachyzoites." (PMID 32413093, 2020).
infection (continued). "In addition, these findings are supported by our prior study in MyD88 KO mice, where animals were exquisitely sensitive to craniotomy infection, since MyD88 is required for both TLR2 and IL-1R signaling, revealing the consequences of negating redundant bacterial recognition pathways." (PMID 32290861, 2020). "Indeed, the lack of correlation between bacterial burden and survival in MyD88-deficient mice reinforces our previous conclusion using WT mice that severe and fatal ehrlichiosis is not due to an overwhelming infection, but rather due to immunopathology." (PMID 31134081, 2019). "Similarly, we have found that mutation in myd88 leads to a large difference in the zebrafish gene expression profile, even in the absence of pathogenic infection." (PMID 31747871, 2019). "Thus, both detection of NMII GE by qPCR and immunohistochemical staining of NMII consistently showed significantly higher bacterial burden in Myd88−/− organs after intraperitoneal infection, which was more pronounced at the later time point (day 20) after infection." (PMID 30800124, 2019). "Notably, mice deficient for MyD88 showed increased non-canonical NF-κB signaling in the stomach upon H. felis infection when compared to WT animals after 25 and 47 weeks of infection." (PMID 31065023, 2019). "Here, we show that MyD88−/− mice are unable to eliminate attenuated Salmonella enterica serovar Typhimurium, even when challenged with a low-dose inoculum (200 CFUs/mouse), developing a persistent and progressive infection when compared to wild-type (MyD88+/+) animals." (PMID 29973931, 2018). "In this study, components of Toll pathway such as Spätzle, Myd88, cactus, and toll-interacting protein showed a downregulated expression in response to B. thuringiensis with Spätzle showing an 8-fold downregulation at the early stage of infection 6 h postinfection, compared to the control." (PMID 30498450, 2018). "However, the tssK-5 mutant caused rapidly fatal infections in mice lacking the innate immune adapter molecule MyD88, which contributes to neutrophil recruitment and activation in mice infected with B. pseudomallei." (PMID 30687298, 2018). "Knowing whether the same, or different, MyD88-dependent receptors and signaling events as those regulating inflammation are also involved in MyD88-dependent epithelial barrier function will be important for developing related therapies to combat inflammation or infection." (PMID 29062042, 2017). "However, no signs of infection were detected in inoculated uninjured corneas from either MyD88 or IL-1R-deficient mice." (PMID 28796783, 2017). "Our results revealed, for the first time, the critical role of T cell-intrinsic IL-18R/MyD88 signaling for mounting a robust Th1 cognate response, as a consequence of proliferation, protection from apoptosis and expression of activation/memory genes during infection with an intracellular pathogen." (PMID 28895840, 2017). "Importantly, our experiments also demonstrate a critical contribution of IEC-intrinsic MyD88 signaling for maintaining the epithelial barrier during infection, together highlighting the importance of MyD88 in both DC and IEC for the induction of the host defense in the intestine." (PMID 28520792, 2017). "In the present study, because DenV2 infection drove TLR2/MyD88 pathway-dependent Th2-biased immune responses that might facilitate secondary infection with different DenV serotypes, we performed neutralization and ADE assay using Vero cells and BM cell-derived macrophages as targets, respectively." (PMID 29285314, 2017). "However, the Dot/Icm apparatus itself did not trigger this cell death response because infections with L. dumoffii, which encodes a homologous Dot/Icm system, did not induce host cell death in Myd88-/- BMMs even when MTOR inhibitors were present." (PMID 27942021, 2016).
infection (continued). "Moreover, even if mice deficient for MyD88 are more susceptible than wild-type animals to MCMV infection, this can be compensated by other modalities of innate sensing of the infection, namely in our experimental set-up by direct NK cell recognition of infected cells." (PMID 25954804, 2015). "This has been shown in mice (Myd88-/- and Tlr2-/- mice have significant immune and host defense defects) as well as in humans (TLR2 expression and a Tlr1 polymorphism are associated with altered immune response to B. burgdorferi OspA vaccination and B. burgdorferi RST1 infection, respectively)." (PMID 26252010, 2015). "Whilst the direct functional effects of the rs6853 SNP, located within the 3’ untranslated region of MYD88, are not currently known, it has been associated with decreased vaccine response and increased susceptibility to infection, as well as electroencephalogram spindle amplitude during anaesthesia." (PMID 26332828, 2015). "However, it has been claimed that the requirements for pDC and endosomal TLR in IFN-I production differ fundamentally during natural infections of men and experimental challenges of laboratory mice, since IRAK4 or MyD88 genetic deficiencies only increase susceptibility to viruses in mice." (PMID 25954804, 2015). "In this article, we set out to investigate how immunity to H. polygyrus was affected when C57BL/6 mice, which typically are chronically susceptible to infection with this parasite, lacked the adapter protein MyD88, a major mediator of signaling through TLRs and IL-1 family members." (PMID 25114104, 2014). "Thus, MyD88 expressed by alveolar macrophages and neutrophils is essential for initiation of an adequate early innate immune response in the lung after infection with Klebsiella via the airways and the absence thereof results in uncontrolled bacterial growth and death." (PMID 25254554, 2014). "In this context, the remaining levels of produced chemokines and recruited neutrophils in MyD88-deficient mice could result in the activation of Nod1 and Nod2, which was not enough to control the infection and resolve the septic episode." (PMID 25084278, 2014). "Previous work has clearly demonstrated that, for both L. major and L. (Viannia) braziliensis, the absence of MyD88-dependent signaling pathways modulated the Th1/Th2 balance following in vivo footpad infection and resulted in increased susceptibility to infection." (PMID 24801628, 2014). "Consequently, mice lacking MyD88 exhibit impaired recruitment of neutrophils to the site of infection and a higher susceptibility to GAS challenge." (PMID 25325020, 2014). "Moreover, MyD88-deficient mice were more susceptible to polymicrobial infection induced by cecal bacteria isolated from WT, suggesting that the observed effect in MyD88-deficient mice was not due to differences in the microbiota between both strains of mice." (PMID 25084278, 2014). "Interestingly, MyD88 signaling within IEC had little impact on the host response to infection." (PMID 23950714, 2013). "In contrast, the activation of MyD88-independent signalling may present an alternative route used by host macrophages to circumvent suppressed MyD88-dependent signalling and induce downstream transcription factors which promote chemokine and cytokine production during infection." (PMID 22384131, 2012). "However, infection of cells deficient for expression of the TLR adaptor proteins TRIF and MyD88 still produces cytokines in response to this protozoan, suggesting that other TLR-independent pathways also may be activated during the early immune response." (PMID 21869919, 2012). "However, six days post infection these cyto- and chemokines were secreted MyD88-independently." (PMID 22096480, 2011). "Furthermore, TLR2 and the TLR adaptor protein MyD88 are critical for host defense against Francisella infection since mice lacking these proteins are more susceptible to infection than their wild-type counterparts." (PMID 21698237, 2011).
infection (continued). "The absence of a detectable neutralizing antibody titer in Myd88-deficient or CD11c+ DC-deleted mice could reflect a general loss of serum antibodies to F-MLV or a defect specifically in antibodies that neutralize infection." (PMID 19214214, 2009). "Moreover, TLRs may be involved in NFκB activation (at 24 h post-infection) since blocking MyD88 function diminished NF-κB activation in HPIV3 infected cells by 50%-55%." (PMID 19922606, 2009). "Infection with avirulent BS103 Shigella primed the NAIP–NLRC4 inflammasome in a TLR2- and MYD88-dependent manner." (PMID 41533441, 2026). "The infection with S. Typhimurium significantly increased TLR4, MD‐2, LBP, CD14, and MyD88 mRNA in both parts of the intestine." (PMID 41474380, 2026). "In mouse models of infection, CD4+ T cells differentiate into Th1/Th17 effector cells in the lung through a MyD88- and inflammasome-dependent process." (PMID 40558085, 2025). "Consistent with the decreased circulating LPA in DKK1(PKO) and MyD88(PKO) infected mice, data showed reduced NPA at the infection site of DKK1(PKO) and MyD88(PKO) infected mice on day 3 PI compared to BALB/c-infected mice." (PMID 40502169, 2025). "At the peak of infection (72 h) fifty-one genes, such as IFNβ, TRAF2, MYD88 and C7b, were exclusively up-regulated." (PMID 40906234, 2025). "During infection of macrophages by C. albicans, pro-IL-1β transcription is regulated through both TLR2/MyD88 and CLR/Dectin-1/SYK pathways, activating the downstream CARD9/BCL10/MALT1 complex that is essential for IL-1β secretion." (PMID 41249509, 2025). "Cxcl10, co-regulated by MyD88/NF-κB and IRF3, recruits CD8+ T cells and NK cells to infection sites, such as vaccine injection sites." (PMID 40573198, 2025). "In vitro infection with C. sakazakii led to increased abundance of IL-1β, TLR4, the inflammasome components NLRP3 and caspase-1, and the adapter protein MyD88 in human colon HT-29 cells." (PMID 41283989, 2025). "The expression of Myd88, IRAK4, and TRAF6 mRNA in both WT and WUCI significantly increased and reached their peak when they were infected with A. hydrophila on day 1 post-infection." (PMID 40298788, 2025). "In a tilapia infection model, Nb30 effectively reduced GBS colonization in the liver, spleen, and brain of Nile tilapia, accompanied by a downregulation of TLR/MyD88/NF-κB pathway-related inflammatory genes and improved survival rates of infected fish." (PMID 41227537, 2025). "We previously characterized the influence of MyD88 on ILC populations of the LP and peritoneal cavity during infection with T. gondii." (PMID 40299872, 2025). "The results showed that the gene expressions of TLR, MyD88, TRAF, NF-κB, IKK, and AP-1 in the (Va + MR) group peaked at 6 h of post infection (P < 0.05)." (PMID 40759806, 2025). "To study the innate immune regulators of HCMV spread following an in vitro infection, we infected MRC-5 cells with an MOI of 0.05 and monitored the level of the innate immune signaling adapter MyD88 by western blot." (PMID 40638072, 2025). "Further, the percentage and number of neutrophils at the infection site of DKK1(PKO) and MyD88(PKO) infected mice were significantly reduced on day 3 PI." (PMID 40502169, 2025). "The results showed that high level-/long time-H37Ra infection downregulated the phosphorylation level of NF-κB as well as the expression of TLR4, TRAF6, and MyD88." (PMID 40502714, 2025). "In the current study, we observed that the MYD88 gene is enriched following IBV DMV/1639 infection at 3 h and IBV Mass41 infection at 18 h." (PMID 38675946, 2024). "For example, infections with Coxsackie virus B3, Venezuelan equine encephalitis virus (VEEV), or Marburg virus significantly increased MyD88." (PMID 39125989, 2024). "In this way, MyD88 interaction with IRF3/IRF7 in a MyD88-independent immune signaling pathway exerts weak immune signaling and curtails IFN-β induction, which is critical for clearing infection at an early stage." (PMID 39125989, 2024).
infection (continued). "During NDV infection in wild-type (WT) mice, pDCs resist infection and produce IFN via an endosomal Myd88-dependent pathway." (PMID 38777879, 2024). "Transcriptomic analysis revealed that ΔfliL strain infection in hybrid groupers activated the TLR5-mediated NF-κB pathway and transcription factor AP-1 in the MyD88 pathway, resulting in an effective immune response." (PMID 39026675, 2024). "Here, we observed higher TLR2, TLR4, TLR5, TLR6, TLR8, TLR9, Myd88, NLRP3, ASC, and TNF-α mRNA expression at seven weeks after infection by S. mansoni in BALB/c and C57BL/6 mice compared to Swiss mice." (PMID 38896633, 2024). "Particularly, mixed-species infection increased the expression of TLR2/4, Nox2/4, and Toll/IL-1R domain-containing adaptor proteins such as MyD88 and TRAF6." (PMID 38700089, 2024). "Our study showed that in the early stage of S. mansoni infection (two weeks post infection) Swiss mice showed higher expression of TLR4, TLR6 and Myd88 mRNA in the liver than BALB/c and C57BL/6." (PMID 38896633, 2024). "They showed lower concentrations of the MyD88-dependent cytokines TNF-α, IL-6 and G-CSF – all involved in the early stages of infection – thus suggesting the inability of RR in mounting an immediate inflammatory response." (PMID 39723217, 2024). "All of this is consistent with previous reports showing that lincRNA-Cox2 is overexpressed in a MyD88-dependent manner in response to the activation of various TLRs such as TLR2, TLR4, TLR7/8, or in response to infection with Listeria monocytogenes." (PMID 38464511, 2024). "Both MyD88 and TRIF adaptor protein mRNA expression showed an apparent trend related to the infection." (PMID 38003758, 2023). "infection in different species, including bovine, via Toll-like receptor 2 (TLR2) binding and MyD88-dependent signaling." (PMID 36692289, 2023). "MyD88 was upregulated as it was in the ileum, but the TRIF mRNA expression was downregulated by the infection with Salmonella." (PMID 38003758, 2023). "Parallelly, in the infection of Plasmodium chabaudi, TLR7 is the primary Myd88-dependent sensor at 24 hours post infection, promoting IFN-α and IFN-β production and a cytokine response (IL-10, TNF, IL-12, and IFN-γ)." (PMID 37180169, 2023). "In a mouse model of infection, blocking the Birc3/TLR4/Myd88 signaling pathway showed a protective effect against carbapenem-resistant K. pneumoniae." (PMID 38274787, 2023). "The Western blotting results showed that TRIF, MAVS, and STING were most effective in inhibition, while MyD88, RIPK2, ASC, and CARD9-BCL10-MALT1 (CBM) were less effective in inhibiting N protein expression at 72 h post-infection." (PMID 37631972, 2023). "In this study, we aimed to determine the relative contributions of MyD88- and TRIF-dependent signaling pathways and the role of macrophages in driving TLR-mediated infection resistance." (PMID 36439136, 2022). "The results showed that after 24 hours of infection with UPEC CFT073, the expression of TLR4, TLR5 and myeloid differentiation Factor 88 (MyD88) mRNA in the 5637 (HTB-9) bladder epithelial cells increased significantly." (PMID 36506014, 2022). "In total, there were 129 proteins identified in this fashion after Myd88−/− BMDM infection, 90% of which were also found after infection of the WT." (PMID 36321832, 2022). "WT, MyD88 KO, and MAVS‐KO THP1 cells produced low levels of CXCL10 at baseline, and these were increased after infection with VZV (Fig EV1D)." (PMID 35670106, 2022). "Significantly, our results showed that the expression of six major adaptor molecules (Myd88, IRAK2, IRAK4, TRAF3, TBK-1 and IRF7) downstream of RNA sensors were dramatically decreased in the PAMs with a PRRSV-ADE infection." (PMID 36680075, 2022). "This was the case for the type I IFN response, but also for RIPK1, STAT1, DDX58, ISG15, TRIM25, and MYD88, involved in TNF-, TLR-, RLR-, and NFκB signaling, 48 h after MOPV infection." (PMID 35337059, 2022).